FUT2 (fucosyltransferase 2 (H blood group))
Diseases named in the same sentence as FUT2 in open-access papers (continued):
Sharing a sentence is not in itself a finding about the gene and the disease.
viral infections (11 papers, 2013 to 2024). "This unexpected result for GII.4 viruses suggests that factors beyond FUT2 expression or levels of HBGA on the cell surface must influence the susceptibility of this cell culture to viral infection." (PMID 39404443, 2024). "The results showed that FUT2 expression affected both the binding of human norovirus to the HIE cell surface and the susceptibility to viral infection, indicating that binding to a molecule glycosylated by FUT2 was critical for human norovirus infection." (PMID 37485533, 2023). "We investigated secretor status because expression of ABO glycans on secreted proteins and non‐erythroid cells are controlled by a fucosyltransferase (FUT2), and inactivating FUT2 mutations result in a non‐secretor phenotype which protects against some viral infections." (PMID 34124710, 2021). "FUT2 polymorphisms may profoundly influence gut microbiota composition and host susceptibility to viral infections and chronic inflammatory disease." (PMID 33425974, 2020). "In the next sections, the role of FUT2 gene variants and associated phenotypes is discussed, with a particular focus on their putative effects on factors associated with T1D development (e.g., viral infections, autoimmune diseases, early life gut microbiota perturbations)." (PMID 33425974, 2020). "In epithelial tissues and secretions, ABO expression is heavily dependent on the inheritance of the Secretor Se/FUT2 gene which can also be protective against viral infection." (PMID 34124710, 2021). "Single nucleotide variants (SNV) that redutce susceptibility to virus infection include a P424A substitution in the filovirus endosomal fusion receptor Niemann-PickC1 (NPC1), and a G428A mutation in fucosyltransferase 2 (FUT2) that renders homozygous carriers resistant to norovirus." (PMID 34524075, 2021). "FUT2 gene variants have been associated with numerous conditions, including the susceptibility to bacterial, fungal or viral infections and (chronic) autoimmune diseases, although results are not univocal." (PMID 33425974, 2020). "Interestingly, these cultures also recapitulate genotype-specific patterns of HuNoV susceptibility as cell cultures with the secretor positive genotype (Fucosyltransferase 2, FUT2) were more susceptible to viral infections than cultures isolated from secretor negative individuals." (PMID 32899147, 2020). "However, a few strains (e.g., Desert Shield virus and VA115) could not bind to any HBGAs, and overexpression of FUT2 in Huh-7 cells was not sufficient to complete viral infection." (PMID 23799113, 2013).
autoimmune disease (10 papers, 2014 to 2026). A disorder resulting from loss of function or tissue destruction of an organ or multiple organs, arising from humoral or cellular immune responses of the individual to their own tissue constituents. "While FUT2 has been associated with autoimmune diseases such as celiac and Crohn’s, its function in these conditions is linked to the secretion of ABO antigens in gastrointestinal mucosa, and no direct connection to glaucoma has been established." (PMID 38287276, 2024). "The FUT2 gene polymorphism has additionally been associated with a diverse set of inflammatory and autoimmune diseases, including Crohn’s disease, celiac disease, Behcet’s disease, type 1 diabetes, and autoimmune neutropenia of early childhood." (PMID 36922975, 2023). "Studies have suggested that a greater proportion of non-secretors exist within populations of patients with type-1-diabetes than within the general population, indicating a possible association between autoimmune disease and FUT2 expression." (PMID 32722157, 2020). "In addition, the FUT2 locus is a well-documented autoimmune disease associated region, including for T1D51,52." (PMID 36316364, 2022). "Furthermore, we identify strong associations between antibodies against 34 viruses and genetic variants at HLA, FUT2, IGH and IGK loci, some of which increase autoimmune disease risk." (PMID 41699059, 2026). "ABO and FUT2 all contribute to both autoimmune diseases and COVID-19." (PMID 38400850, 2024). "Although the current knowledge does not support a clear-cut association between FUT2 gene variants and the development and progression of autoimmune diseases, the interaction between FUT2 phenotype and the immune system is a promising target to be explored." (PMID 33425974, 2020). "Interestingly, the wild-type allele associated with viral gastroenteritis susceptibility inversely appears to be protective against several inflammatory or autoimmune diseases for yet unclear reasons, although a FUT2 influence on microbiota composition has been observed." (PMID 36922975, 2023). "However, robust evidence linking FUT2 gene variants to autoimmune diseases is still lacking." (PMID 33425974, 2020).
Rotavirus infection (10 papers, 2017 to 2025). Infection with any of the rotaviruses. "Most have concluded that the presence of at least one of the genes (FUT2 and FUT3) encoding HBGA has been associated with greater susceptibility to rotavirus infection." (PMID 36560739, 2022). "In order to evaluate the role of HBGAs in rotavirus infections in our population, secretor status (FUT2+), ABO blood group, and Lewis antigens were determined in children attended for rotavirus gastroenteritis in Valencia, Spain." (PMID 30974776, 2019). "Finally, it would have been helpful to determine the FUT3 genotype of the cohort in addition to FUT2, to better comprehend the relationship between rotavirus infections and HBGAs." (PMID 33573340, 2021). "The FUT2 genetics of a population may define the availability of host HBGA receptors for rotavirus infection, which could drive the epidemiology of rotavirus strain circulation in a region." (PMID 32992488, 2020). "Lewis (FUT3) and secretor (FUT2) genes appear to mediatesusceptibility to rotavirus infection.P rotaviruses only infect individuals who are Lewis-positive andsecretor-positive whereas P rotaviruses infect individuals irrespective of theirLewis and secretor status." (PMID 29466164, 2018). "The mechanisms involved remain challenging to elucidate as the pathogenesis of rotavirus infection in traditional in vitro cell culture models appears to be independent of FUT2." (PMID 38535566, 2024). "Unlike human noroviruses, in which infection by certain genogroups is tightly restricted by FUT2 expression, FUT2 expression does not appear to be an absolute restriction factor for rotavirus infection, but rather variably limits viral growth." (PMID 38535566, 2024).
type 1 diabetes (10 papers, 2011 to 2024). "The variant rs601338 in FUT2 has been associated with resistance to Norwalk virus infection, rs10774671 in OAS1 with diabetes type 1 susceptibility, rs3892097 in CYP2D6 with poor metabolism of debrisoquine, and rs3832852 in A2M with the pathogenesis of Alzheimer's disease." (PMID 39368455, 2024).
asthma (9 papers, 2018 to 2025). "In a house dust mite (HDM)-induced asthma model the severity of diseases correlated with increased α1,2-linked fucose residues, while a knockout of Fut2 exhibited reduced asthma features." (PMID 38785919, 2024). "Studies in mice have shown that knockout of the FUT2 gene can reduce eosinophilic inflammation and airway hyperresponsiveness caused by house dust mites, a common trigger for asthma." (PMID 37256139, 2023). "The FUT2–ABO interaction pattern looked similar to the one seen for asthma as illustrated by FUT2 × ABO stratified analysis of the risk of respiratory illnesses with detection of S. pneumoniae." (PMID 33328473, 2020). "We identified a novel susceptibility locus for early childhood asthma on chromosome 19 near the FUT2 gene." (PMID 33328473, 2020). "The main component of mucus, MUC5AC, is typically fucosylated, and FUT2 exacerbates asthma through α-1,2-fucosylation of MUC5AC." (PMID 37256139, 2023). "Here, the authors identify a possible epistatic relationship between coding variants in FUT2 and ABO, especially pronounced in severe and early onset asthma." (PMID 33328473, 2020). "For some conditions, including asthma and arthritis,FUT2 heterozygosity (GA) appeared to confer an intermediate phenotype." (PMID 30345375, 2018). "Since MO-DCs may present allergens to Th-2 lymphocytes, promote T cell stimulation via the OX40 ligand, and produce proinflammatory chemokines such as CCL2 and CCL24 (eotaxin 2), the role of FUT2 in MO-DC accumulation is significant in asthma." (PMID 38785919, 2024). "Homozygous secretors of FUT2 may have more severe asthma exacerbations and poor lung function." (PMID 37256139, 2023). "Nine loci surpassed the genome-wide significance threshold, of which the FUT2/MAMSTR locus on chromosome 19, with the top SNP rs281379 (odds ratio (OR) = 1.18 (95% confidence interval (CI) = 1.11–1.25), Pdiscovery = 2.6 × 10−9), emerged as a novel locus associated with asthma." (PMID 33328473, 2020). "We identified FUT2 and ABO variation, and epistatic effects between the two, as a genetic mechanism increasing the risk of early childhood asthma and hypothesize that this is related to the expression of AB antigens in the respiratory epithelium and involves infection with S. pneumoniae." (PMID 33328473, 2020). "The novel FUT2/MAMSTR signal was replicated in the COPSAC birth cohorts (COPSAC2000 and COPSAC2010 combined), where there was evidence of an association between rs281379 and asthma before the age of 6 years (OR = 1.38 (95% CI = 1.09–1.75), Preplication 1 = 0.008)." (PMID 33328473, 2020). "Although we focused on the potential implications of CHIT1 inhibition in the context of asthma severity and airway remodeling, other enzymes hold therapeutic promise for glycosylation regulation, such as galectins, NEU1, and FUT2." (PMID 38785919, 2024). "Thus, FUT2 and α-1,2-fucosylation may play a crucial role in asthma." (PMID 37256139, 2023). "IL-33 induces the expression of fucosyltransferase 2 (Fut2), and glycation of BECs leads to sustained ILC2 activation in T2 asthma." (PMID 38203353, 2023). "Fucosylation was shown to be associated with greater airway disease severity, and a knockout of FUT2 significantly reduced lung epithelial fucosylation, attenuated eosinophilic inflammation, and decreased airway hyperresponsiveness in HDM-induced asthma models." (PMID 38785919, 2024). "Our study demonstrates that phenotype specificity is important for the ability to detect gene–gene interactions, as evident by a strong interaction observed between the FUT2 and ABO genes only in the most severe asthma cases, as well as in the COPSAC birth cohorts with detailed clinical phenotyping." (PMID 33328473, 2020). "FUT2 may play a key role in MUC5AC regulation leading to excess mucus production or its increased viscosity, a common characteristic observed in patients with airway obstructive diseases including asthma, bronchitis and COPD." (PMID 37263751, 2023).
asthma (continued). "This is likely to be the reason for FUT2 and ABO not being detected in the previous GWAS on asthma, including much larger sample sizes." (PMID 33328473, 2020).
COVID-19 (9 papers, 2022 to 2026). A disease caused by infection with severe acute respiratory syndrome coronavirus 2. "Many follow-up studies have reported ABO and ENPEP as COVID-19 risk genes; however, the evidence for the FUT2 gene is conflicting." (PMID 35736459, 2022). "mGWAS-Explorer was also able to identify ENPEP and FUT2 as potential candidate genes for COVID-19, although the association signal of these two genes were below the genome-wide significance threshold in the original study." (PMID 35736459, 2022). "Finally, the rs48697960 SNP (CT genotype) within the fucosyltransferase 2 (FUT2) gene which regulates expression of the ABO blood group antigens is weakly correlated with increased risk of severe COVID-19 development." (PMID 36941580, 2023). "Moreover, combined analysis of ABO and FUT2 genotypes revealed that the presence of oral AB antigens was significantly associated with the onset of COVID-19." (PMID 35264675, 2022). "Therefore, it may be valuable to perform colocalization analysis and Mendelian randomization studies to identify the causal link between FUT2 variants, fibrinogen A-α peptides, and COVID-19." (PMID 35736459, 2022). "In a subset of 79 children, a genetic analysis was carried out to evaluate the role of common COVID-19 genetic risk factors (chromosome 3 cluster; ABO-blood group system; FUT2, IFNAR2, OAS1/2/3, and DPP9 loci)." (PMID 36873632, 2023). "We found a significant positive genetic correlation of VTE with COVID-19 hospitalization and identified specific shared loci for VTE with each COVID-19 trait in ABO, ADAMTS13 and FUT2 genes, which was involved in coagulation." (PMID 37085521, 2023). "In line with previous studies, we identified ABO gene and FUT2 gene, which contributed to both VTE and COVID-19." (PMID 37085521, 2023). "The cross-trait and co-localization analyses identify 2, 3, and 4 shared loci between venous thromboembolism and severe COVID-19, COVID-19 hospitalization, SARS-CoV-2 infection respectively, which are mapped to ABO, ADAMTS13, FUT2 genes involved in coagulation functions." (PMID 37085521, 2023).
gastroenteritis (9 papers, 2018 to 2024). An inflammatory disorder that affects the upper and lower gastrointestinal tract. "However, other studies demonstrated that gastroenteritis incidence caused by P RVs, antibody titers to P genotypes, and vaccine take are correlated with the FUT2 phenotype." (PMID 32208455, 2020). "A series of recent epidemiological studies conducted in France24, Vietnam25, Burkina Faso26, USA27 and China20 showed that only children of the secretor geno- or phenotype, thus having at least one functional FUT2 allele, were found among those suffering from gastroenteritis caused by P and P RVs." (PMID 30154494, 2018). "Human rotaviruses attach to histo-blood group antigens glycans and null alleles of the ABO, FUT2 and FUT3 genes seem to confer diminished risk of gastroenteritis." (PMID 36970669, 2023). "The FUT2 α1,2fucosyltransferase contributes to the synthesis of fucosylated glycans used as attachment factors by several pathogens, including noroviruses and rotaviruses, that can induce life-threatening gastroenteritis in young children." (PMID 36922975, 2023). "Here, we studied a cohort of young healthy adults and showed that the wild-type FUT2 allele was associated with the presence of anti-RVA antibodies, either neutralizing antibodies or serum IgA, confirming its association with the risk of RVA gastroenteritis." (PMID 36922975, 2023). "The fucosyltransferase 2 gene (FUT2) affects HBGA expression in intestinal epithelial cells; secretors express a functional FUT2 enzyme, while nonsecretors lack this enzyme and are highly resistant to infection and gastroenteritis caused by many HuNoV strains." (PMID 32184242, 2020). "Persons who lack functional FUT2 alleles do not express ABH HBGAs on epithelial cells, are designated nonsecretors, and are highly resistant to gastroenteritis caused by some HuNoV strains such as GII.4 viruses." (PMID 32184242, 2020). "FUT2 genotyping allowed us to identify 18 nonsecretor subjects who had HuNoV shedding in stool, confirming their infection status, with presentation of acute gastroenteritis symptoms in all of them but one." (PMID 33266188, 2020).
psoriasis (9 papers, 2013 to 2025). An autoimmune condition characterized by red, well-delineated plaques with silvery scales that are usually on the extensor surfaces and scalp. "FUT2 gene polymorphism may be involved in metabolic syndrome and psoriasis through the regulation of dyslipidemia." (PMID 34589554, 2021). "We found that the FUT2 variant associated strongly with serum levels of ALP (P = 1.1×10−73) and also with psoriasis (P = 4.3×10−3) as previously reported." (PMID 23754956, 2013). "Common genetic variants such as FUT2, UBE2L3, CDKAL1, SH2B3 and apolipoprotein E are more frequently found in psoriasis patients, having multiple functions that would explain their dual role in susceptibility to psoriasis and MS." (PMID 40003621, 2025). "Another study mapped eQTLs in skin tissues from psoriasis patients and looked at overlap with psoriasis GWAS results, finding significant enrichment of psoriasis GWAS SNPs in their eQTL dataset, with effects on the expression of genes such as FUT2, RPS26 and ERAP2." (PMID 32778885, 2020). "More than 4500 cases and 10,000 controls were investigated in GWAS, where 7 non-HLA susceptibility loci shared by CD and psoriasis (9p24 near JAK2, 10q22 at ZMIZ1, 11q13 near PRDX5, 16p13 near SOCS1, 19p13 near FUT2, 17q21 at STAT3, 22q11 at YDJC) were found." (PMID 36443384, 2022).
allergic disease (8 papers, 2017 to 2025). An immune response that occurs following re-exposure to an innocuous antigen, and that requires the presence of existing antibodies against that antigen. "Using logistic regression models, we studied associations between FUT2-dependent breast milk oligosaccharides and incidence of allergic disease at 2 and 5 years of age." (PMID 34108974, 2021). "Delivery mode was reported to be a significant modifier of the association between the presence of FUT2-dependent oligosaccharides and allergic disease development, although the strata-specific effects were quite weak." (PMID 29732363, 2018). "Moreover, higher concentrations of FUT2-dependent HMOs such as 2′-FL were associated with lower risk of allergy at age 2 and 5 in infants with high hereditary risk of allergy." (PMID 34201331, 2021). "Higher concentrations of FUT2-dependent HMOs such as 2′-fucosyllactose were also correlated with lower risk of allergy at 2 and 5 y of age in infants with high hereditary allergy risk, and HMOs including 2′-fucosyllactose attenuated food allergy symptoms in a mouse model." (PMID 28356278, 2017). "In another study focusing on FUT2-dependent oligosaccharides, it was found that C-section-born children had a lower incidence of allergic disease at 2 years of age when fed with human milk containing FUT2-dependent oligosaccharides." (PMID 40636105, 2025). "Using this dichotomy assumes that infants who consume high concentrations of FUT2-dependent oligosaccharides are just as likely to develop allergic disease as those exposed to low concentrations." (PMID 29732363, 2018).